GLI3 (GLI family zinc finger 3)
Description:
Transcription factor that acts as a key effector of the smoothened signaling pathway, and which plays a role in the development and patterning of various body structures, including the brain and limbs. Specifically binds to the minimal GLI-consensus sequence 5'-GACCACCCA-3' to activate or repress the expression of target genes. Functions both as a transcriptional activator and repressor: the full-length GLI3 form (Transcription activator GLI3) acts as a transcription activator following smoothened activation, while the Transcription repressor GLI3R, which is generated in absence of smoothened, acts as a transcription repressor. The repressor form (GLI3R) constitutes the major form of GLI3. [Transcription repressor GLI3R]: Major transcription repressor, which inhibits expression of target genes in the absence of smoothened (SMO) signaling. Generated by proteolytic processing of the full-length GLI3 form in the absence of hedgehog (DHH, IHH or SHH), when SMO transducer is inhibited. Constitutes the major form of GLI3, while the transcription activator form only plays a minor role. [Transcription activator GLI3]: Transcription factor, which activates expression of target genes in response to smoothened (SMO) activation. Constitutes a minor form of GLI3, while the transcription repressor form (GLI3R) plays a major role. In concert with TRPS1, plays a role in regulating the size of the zone of distal chondrocytes, in restricting the zone of PTHLH expression in distal cells and in activating chondrocyte proliferation.
Synonyms: GLI3-190; GLI3FL; PAP-A; PAPA; PAPA1; PAPB; ACLS; PPDIV; GCPS; PHS
Tractability: PROTAC: UniProt records ubiquitination sites on it; ubiquitination databases record sites on it.
Gene: Protein-coding gene on chromosome 7 (41,960,949 to 42,264,265, reverse strand). Ensembl gene ENSG00000106571.
Subcellular location: Nucleus; Cytoplasm; Cell projection, cilium; Nucleus (Transcription repressor GLI3R); Nucleus (Transcription activator GLI3)
Subcellular location (Human Protein Atlas): Nucleoplasm; Nucleoli; Vesicles
Pathways (Reactome):
Signal Transduction: GLI proteins bind promoters of Hh responsive genes to promote transcription; GLI3 is processed to GLI3R by the proteasome; Hedgehog 'off' state; Hedgehog 'on' state
Gene expression (Transcription): RUNX2 regulates osteoblast differentiation
Gene Ontology:
Molecular function: beta-catenin binding; DNA-binding transcription factor activity; histone acetyltransferase binding; histone deacetylase binding; mediator complex binding; protein binding; RNA polymerase II cis-regulatory region sequence-specific DNA binding; RNA polymerase II transcription regulatory region sequence-specific DNA binding; sequence-specific double-stranded DNA binding; DNA-binding transcription factor activity, RNA polymerase II-specific; chromatin binding; double-stranded DNA binding; sequence-specific DNA binding
Biological process: limb morphogenesis; negative regulation of canonical Wnt signaling pathway; negative regulation of DNA-templated transcription; negative regulation of transcription by RNA polymerase II; positive regulation of transcription by RNA polymerase II; regulation of DNA-templated transcription; smoothened signaling pathway; embryonic digestive tract development; embryonic digit morphogenesis; negative regulation of alpha-beta T cell differentiation; negative regulation of smoothened signaling pathway; negative thymic T cell selection; nose morphogenesis; positive regulation of alpha-beta T cell differentiation; positive regulation of DNA-templated transcription; regulation of transcription by RNA polymerase II; T cell differentiation in thymus; thymocyte apoptotic process; anatomical structure morphogenesis; limb development; regulation of gene expression
Cellular component: cilium; cytoplasm; cytosol; GLI-SUFU complex; non-motile cilium; nucleus; ciliary base; ciliary tip; nucleoplasm; axoneme; nuclear speck; transcription repressor complex
Genetic constraint (gnomAD): Loss-of-function variants: 20 observed, 97.41 expected, observed/expected ratio (o/e) 0.21, 90% interval 0.14 to 0.3. The upper end of that interval is the gene's LOEUF score, 0.3, which puts it in group 1 of 6, group 1 being the genes least tolerant of losing a copy. Missense variants: 1,993 observed, 2,127.6 expected, observed/expected ratio (o/e) 0.94, 90% interval 0.9 to 0.97. Synonymous variants: 921 observed, 874.34 expected, observed/expected ratio (o/e) 1.05, 90% interval 1 to 1.11.
Gene-disease validity (ClinGen):
ClinGen rates the evidence that GLI3 causes each of these diseases.
Greig cephalopolysyndactyly syndrome (autosomal dominant): Definitive. Greig cephalopolysyndactyly syndrome (GCPS) is a pleiotropic, multiple congenital anomaly syndrome.
Homologues: Orthologues: chimpanzee GLI3 (99% identical), macaque GLI3 (99% identical), rabbit GLI3 (90% identical), guinea pig GLI3 (88% identical), mouse Gli3 (87% identical), pig GLI3 (87% identical), rat Gli3 (86% identical), dog GLI3 (85% identical), tropical clawed frog gli3 (69% identical), zebrafish gli3 (51% identical). Paralogues in human: GLI2 (45% identical), GLI1 (25% identical), GLIS3 (15% identical), GLIS1 (14% identical), GLIS2 (12% identical), ZIC5 (10% identical), ZIC2 (10% identical), ZXDC (10% identical), ZIC1 (9% identical), ZIC3 (9% identical), ZXDA (8% identical), ZXDB (8% identical), and 2 more.
Diseases named in the same sentence as GLI3 in open-access papers:
GLI3 is named in the same sentence as 204 diseases in open-access papers, as found by Europe PMC text mining. Sharing a sentence is not in itself a finding about the gene and the disease. The quoted sentences say what the papers report.
Greig cephalopolysyndactyly syndrome (45 papers, 2007 to 2025). "CMA showed a female profile with a pathogenic variant of the GLI3 gene, confirming the diagnosis of Greig cephalopolysyndactyly syndrome." (PMID 38369506, 2024). "Further genetic testing revealed a female profile with a pathogenic variant of the GLI3 gene, confirming a diagnosis of Greig cephalopolysyndactyly syndrome." (PMID 38369506, 2024). "Pathogenic DNA variants in the GLI-Kruppel family member 3 (GLI3) gene are known to cause multiple syndromes: for example, Greig syndrome, preaxial polydactyly-type 4 (PPD4) and Pallister-Hall syndrome." (PMID 32591344, 2021). "This patient also displayed polydactyly and syndactyly, two hallmark clinical features of humans with GLI3-Greigs cephalopolysyndactyly syndrome (GCPS), which corresponds to the loss of GLI3 transcriptional repression during limb development." (PMID 31767679, 2020). "GLI3 mutations were found to be involved in two developmental syndromes: Pallister-Hall syndrome and Greig cephalopolysyndactyly syndrome." (PMID 30754706, 2019). "Autosomal dominant mutations in GLI3 are described in the Pallister–Hall syndrome (OMIM 146510) or in the Greig cephalopolysyndactyly syndrome (OMIM 175700)." (PMID 31555317, 2019). "In case 5, an approximately 3 Mb deletion in 7p14.1-p13 was found, disrupting the GLI3 gene associated with Greig cephalopolysyndactyly syndrome (OMIM 175700), which was concordant with the fetal dysmorphic phenotype." (PMID 24689080, 2014). "This conclusion differs from a recent report that describes a haploinsufficient heterozygous mutation in GLI3 in a subpopulation of congenital mastocytosis with Greig cephalopolysyndactyly syndrome and implicates the canonical HH-pathway in aggressive mastocytosis and cultured neoplastic mast cells." (PMID 35251038, 2022). "However, in one case, the postnatal genetic test detected a mutation in GLI3-gene, which causes Greig cephalopolysyndactyly syndrome, which is associated with craniosynostosis." (PMID 34633507, 2022). "Mutations affecting GLI3 are responsible of different syndromic conditions, including the Greig cephalopolysyndactyly syndrome (OMIM 175700), the Pallister–Hall syndrome (OMIM 146510) and the Postaxial polydactyly type-A (OMIM 174200), but none of such conditions are associated with WT development." (PMID 30344923, 2018). "Heterozygous mutations in Gli3 account for several dominant diseases of variable severity, including Greig cephalopolysyndactyly syndrome (GCPS; MIM: 175700), Pallister-Hall syndrome (MIM: 146510), preaxial polydactyly type IV (MIM: 174700) and postaxial polydactyly types A1 and B (MIM: 174200)." (PMID 30463396, 2018). "Truncation mutations of the GLI3 zinc finger transcription factor, a human homologue to Cubitus interruptus, can cause Greig cephalopolysyndactyly syndrome, a pleiotropic, multiple congenital anomaly syndrome with low frequency central nervous system anomalies, hernias, and cognitive impairment." (PMID 19855832, 2009). "Mutations in Gli3 result in a shortened cell cycle, impaired cortical lamination, and cortical neuron formation and are responsible for various morphological CNS abnormalities, such as Greig cephalopolysyndactyly syndrome (GCPS), Pallister-Hall syndrome (PHS) and polydactyly and syndactyly." (PMID 39764159, 2024). "GLI3 pathogenic variants cause non-syndromic and syndromic polydactyly, including the rare autosomal dominant Greig cephalopolysyndactyly syndrome (GCPS, OMIM accession 175700)." (PMID 30937429, 2019). "Mutations in different domains of the GLI3 gene underlie several congenital diseases including Greig cephalopolysyndactyly syndrome (GCPS) and Pallister-Hall syndrome (PHS)." (PMID 29368652, 2018). "Inactivating mutations in Gli3 and Ptc1 have been identified in humans with Greig Cephalopolysyndactyly Syndrome (GCPS) and Nevoid Basal Cell Carcinoma Syndrome (NBCCS, also known as Gorlin Syndrome) respectively." (PMID 19809516, 2009).
Greig cephalopolysyndactyly syndrome (continued). "Gli3 mutations cause limb development disorders, such as Greig cephalopolysyndactyly syndrome (GCPS), Pallister-Hall syndrome (PHS), postaxial polydactyly type A (PAP-A) and preaxial polydactyly type IV." (PMID 19925654, 2009). "The 14.8-Mb inversion disrupts GLI3, and the affected individuals had features consistent with Greig cephalopolysyndactyly syndrome." (PMID 38776926, 2024). "In addition, the variants in GLI3 have been identified in patients of Greig cephalopolysyndactyly syndrome (GCPS, OMIM #175700) and Pallister-Hall syndrome (PHS, OMIM #146510)." (PMID 38884091, 2024). "The macrosomia, hypertelorism, prominent metopic suture without confirmed craniosynostosis, anomaly of the corpus callosum, and polysyndactyly can be attributed to Greig cephalopolysyndactyly syndrome and haploinsufficiency of GLI3." (PMID 34828280, 2021). "Lastly, a human deletion in GLI3 was associated with causing subclinical autism in the father of a child with ASD and Greig cephalopolysyndactyly syndrome." (PMID 34573345, 2021). "Using the ID gene GLI3 as an example, a clear and simplistic description of several heterogeneous diseases would be GLI3-related Pallister-Hall syndrome or GLI3-related Greig cephalopolysyndactyly syndrome." (PMID 34930158, 2021). "In humans, there is a subset of male patients with mutations in GLI3, including autosomal dominant GLI3 anomalies categorized as Greig cephalopolysyndactyly syndrome (GCPS) and Pallister-Hall syndrome (PHS), that exhibit differences in male sex differentiation." (PMID 32497091, 2020). "Mutations in GLI3 have been shown to cause several Mendelian disorders associated with craniofacial and limb abnormalities, including GCPS (Greig cephalopolysyndactyly syndrome)." (PMID 27193062, 2016). "Greig cephalopolysyndactyly syndrome (GCPS) and isolated preaxial polydactyly type IV (PPD-IV) are rare autosomal dominant disorders, both caused by mutations in the GLI3 gene." (PMID 22903559, 2012). "We tested the SV40 promoter as a strong promoter that was inserted into the pGL SV40 plasmid, and we used the minimal promoter of the human GLI3 gene (NM_000168; Greig cephalopolysyndactyly syndrome; MIM #175700) as an example of a relatively weak promoter." (PMID 21826217, 2011). "Mutations in the transcription factor GLI3, a downstream target of Sonic Hedgehog (SHH) signaling, are responsible for the development of malformation syndromes such as Greig-cephalopolysyndactyly-syndrome (GCPS), or Pallister-Hall-syndrome (PHS)." (PMID 19829694, 2009). "Notably, 5/6 cases with variants of CCM2 had no single nucleotide variants but deletions of variable size that can also encompass additional flanking genes, including GLI3, leading to two cases of Greig cephalopolysyndactyly syndrome." (PMID 36198887, 2023). "Greig cephalopolysyndactyly syndrome (GCPS; OMIM number: 175700), Pallister-Hall syndrome (PHS; OMIM number: 146510), and postaxial polydactyly type A1 and type B3 (PAPA1 and PAPB; OMIM number: 174200) are resulted from heterozygous mutations of GLI3." (PMID 32933018, 2020). "Greig cephalopolysyndactyly syndrome (GCPS, MIM#175700) and isolated preaxial polydactyly type IV (PPD-IV, MIM#174700) are rare autosomal dominant disorders, both caused by mutations in the GLI3 zinc-finger transcription factor gene." (PMID 22903559, 2012). "The role of GLI genes in development was first revealed by the discovery of deleterious variants in GLI3 in several human congenital malformations, including Pallister–Hall syndrome (PHS), Greig cephalopolysyndactyly syndrome (GCPS), non-syndromic polydactyly, and acrocallosal syndrome." (PMID 33304378, 2020). "Mutations in the human GLI3 gene cause a variety of dominant developmental syndromes subsumed as "GLI3 morphopathies", including Greig cephalopolysyndactyly syndrome (GCPS), Pallister Hall syndrome (PHS), postaxial polydactyly type A (PAPA), and preaxial polydactyly type IV (PPD-IV)." (PMID 20426846, 2010).
Greig cephalopolysyndactyly syndrome (continued). "Variants located in different GLI3 structural domains can lead to different congenital disorders, including Greig cephalopolysyndactyly syndrome (GCPS; MIM 175700), Pallister–Hall syndrome (PHS; MIM 146510), non-syndromic PAP (PAP-A/B; MIM 174200), and PPD type IV (PPD-IV; MIM 174700)." (PMID 41142227, 2025).
Pallister-Hall syndrome (35 papers, 2006 to 2025). Pallister-Hall syndrome (PHS), a pleiotropic autosomal dominant malformative disorder, is characterized by hypothalamic hamartoma, pituitary dysfunction, bifid epiglottis, polydactyly, and, more rarely, renal abnormalities and genitourinary malformations. "Rather mutations in GLI3 which result in a functional, repressive protein, are linked to Pallister Hall Syndrome (PHS) an autosomal dominant disorder characterised by postaxial polydactyly, imperforate anus, hypothalamic hamartoma and hypopituitarism." (PMID 37794731, 2024). "A diagnosis of Pallister-Hall Syndrome is met upon the criteria of hypothalamic hamartoma, mesoaxial polydactyly, and a confirmed mutation in the central-third of the GLI3 gene." (PMID 37675356, 2023). "Pallister-Hall syndrome is inherited in an autosomal dominant pattern typically due to a GLI3 frameshift gene mutation." (PMID 35251807, 2022). "Pallister-Hall syndrome (OMIM #146510) is a rare autosomal dominant condition caused by a mutation in the GLI3 gene." (PMID 35331151, 2022). "Further analysis is required to fully appreciate the functional differences between truncating mutations that cause Pallister-Hall syndrome and those that result in GLI3-mediated polydactyly syndromes." (PMID 32591344, 2021). "The GLI3-associated syndromes encompass polydactyly, central nervous system, and lungs pathologies, associating in Greig cephalopolysyndactyly and Pallister-Hall syndromes, presenting only autosomal dominant mode of inheritance." (PMID 32696176, 2021). "Gli3 is necessary for the correct development of the apical region of the cochlea and its mutation causes Pallister-Hall syndrome which shows a prevalence of low-frequency HL." (PMID 33015071, 2020). "On the other hand, Pallister-Hall syndrome is a result of heterozygous dominant active mutations that produce a truncated Gli3 that functions as a constitutive repressor." (PMID 30754706, 2019). "Mutations in GLI3 have been shown to cause Greig cephalopolysyndactyly, Pallister-Hall syndrome and non-syndromic polydactyly." (PMID 25267529, 2014). "Germ line mutations in GLI3 have been implicated in two human developmental disorders: Pallister-Hall syndrome and Grieg cephalopolysyndactyly syndrome." (PMID 20865152, 2010). "Truncating GLI3 mutations in Pallister-Hall Syndrome with renal malformation suggests a requirement for Hedgehog signaling during renal development." (PMID 19809516, 2009). "Genotype-phenotype correlation has been reported for Pallister-Hall syndrome with mutations deleting the C-terminal part of GLI3, 3′of the zinc finger encoding domain, leaving the DNA-binding domain intact." (PMID 17426814, 2007). "In humans, a number of different mutations to the GLI3 allele can cause Greig cephalopolysyndactyly (GCPS) or Pallister-Hall Syndrome (PHS)." (PMID 17029624, 2006). "Both GCS and Pallister-Hall syndrome (PHS) are caused by variants in GLI3." (PMID 36411030, 2023). "Loss of function mutations of GLI3 determine the classic phenotype with craniofacial dysmorphism (macrocephaly, hypertelorism) and polysyndactyly; while gain of function mutations determine the Pallister-Hall syndrome (MIM# 146510)." (PMID 34828280, 2021). "Pallister-Hall syndrome (PHS) is an extremely rare syndrome of unknown prevalence with autosomal dominant inheritance due to GLI3 gene mutations classically characterized by the presence of a hypothalamic hamartoma and polydactyly." (PMID 31011455, 2019). "Pallister-Hall syndrome is a rare autosomal dominant condition that is associated with polydactyly and hypothalamic hamartoma and is caused predominantly by frameshift or nonsense pathogenic variants in the GLI3 gene." (PMID 30455963, 2018).